CRP (C-reactive protein)
Diseases named in the same sentence as CRP in open-access papers (continued):
Sharing a sentence is not in itself a finding about the gene and the disease.
depression (continued). "Although previous studies have found the functional relevance of gut microbiome and CRP with the development of anxiety and depression, the biological mechanism underlying the effects of interaction between gut microbiome and CRP on the risks of anxiety and depression remains to be elucidated." (PMID 34481527, 2021). "Furthermore CRP is among the inflammatory signal molecules with the strongest relationships with depression and is easily obtained and analyzed in hospital laboratories, rendering it readily utilizable in a clinical context." (PMID 34764926, 2021). "A large number of literature reports indicated that there was a deterministic relation between higher CRP level, change in brain structure, and depression, still the relationship between peripheral inflammation, brain structure, and depression remains unclear." (PMID 33599398, 2021). "Several authors confirmed a poorer quality of life in children and adults with FMF and a higher incidence of anxiety and depression that may lead to more frequent attacks with higher rates of CRP and SAA." (PMID 34858402, 2021). "Furthermore, meta-analyses assessing various cytokine levels after anti-depressant treatment in people with depression show significant decreases in IL-6, IL-1β, and CRP." (PMID 39296317, 2021). "A Danish study found a higher use of primary healthcare as well as a higher rate of positive tests (C-reactive protein, Strep A test, Urinary stix) in children of mothers with depression which could be interpreted as a higher rate of infectious disease." (PMID 33743653, 2021). "First, suicidality may become a useful symptom (characteristic of inflammatory activity beyond CRP levels) for stratification efforts in RCTs of immunotherapy in depression." (PMID 33079133, 2021). "Nevertheless, ENS patients with preoperative hs-CRP levels > 2.02 mg/L still could expect a 55% chance to remain non-depression status after surgical treatment." (PMID 34943627, 2021). "Testing CRP levels in overweight patients with depression could be useful for recommending adjunct anti-inflammatory treatments or predicting their likelihood of developing additional comorbidities in the future." (PMID 33731235, 2021). "Indeed, some genetic epidemiological studies have shown significant associations between the severity of depression and polymorphisms in inflammatory cytokine genes encoding IL-1β, IL-6, TNF and CRP." (PMID 34351967, 2021). "The prevalence of elevated CRP (>1 mg/L) in depression is 58%." (PMID 33672126, 2021). "For instance, in major depressive disorder, CSF CRP strongly correlates with plasma CRP." (PMID 34680430, 2021). "The “usual suspects” associated with depression tend to be elevated interleukins (ILs), interferons (IFNs) and acute phase proteins, including IL-1β, IL-6, IL-2, IFN-γ, tumour necrosis factor alpha (TNF-α) and C-reactive protein (CRP)." (PMID 34816138, 2021). "However, the role of interaction between gut dysbiosis and C-reactive protein (CRP) in the development of anxiety and depression remains to be elucidated." (PMID 34481527, 2021). "Notably, CRP values have been used to predict the outcome of depression and resistance to standard antidepressants." (PMID 34777034, 2021). "Results for a full logistic regression model indicate that the association between depression and all current e-cigarette use status was not moderated by CRP level (p-value = 0.361)." (PMID 34639705, 2021). "Additionally, given interest in other potential markers of inflammation in relation to depression treatment response, we also explored relationships between several other inflammatory markers including CRP, IL-6, IL-10, TNF-α, and ketamine treatment outcome." (PMID 33723220, 2021). "There is heterogeneity of effect size between studies that may be attributable to clinical variability, with higher CRP in severe depression than in mild/moderate depression." (PMID 34934041, 2021).
depression (continued). "Plasma CRP in depression was not only positively associated with plasma levels of inflammatory cytokines (e.g., IL-6, TNF-α, sTNFR2, and IL-1ra), but also correlated with the level of CRP in cerebrospinal fluid." (PMID 34975571, 2021). "Whether this recent CRP elevation could be a mediating factor for links between depression and past psychological stress, abuse/maltreatment is an important hypothesis that needs to be tested in further prospective samples." (PMID 31707310, 2020). "Notably, the patient rates with high CRP levels varied according to the examined subjects, being higher in people with a positive history of depression and treatment resistance, child abuse, or other comorbid medical diseases and metabolic syndromes." (PMID 32517269, 2020). "Meta-analyses confirm increased circulating C-reactive protein (CRP) levels in depression." (PMID 31707310, 2020). "Therefore, the findings to date, at least for markers that show elevations of the mean and reductions in heterogeneity such as CRP, support a narrower distribution that is shifted to the right in depression." (PMID 32113908, 2020). "The link between depression and inflammation was initially suggested by clinical results showing that depression is accompanied by an upregulated inflammatory response, such as increased production of proinflammatory cytokines and acute CRP." (PMID 32545890, 2020). "Patients with depression exhibit increased peripheral blood concentrations of CRP." (PMID 33213019, 2020). "Based on these reports, it was suggested that peripheral blood IL-1β, IL-6, TNF, and CRP could constitute reliable biomarkers of inflammation in patients with depression." (PMID 32380663, 2020). "Other inflammatory markers besides CRP and hsCRP were also examined in relation to depression." (PMID 31019266, 2020). "Recently, correlations between inflammation markers (neopterin and CRP) and depression scores in a population of patients with solid tumors were reported, and particularly in male patients, lower Trp levels were associated with higher depression scores and stronger fatigue." (PMID 32153576, 2020). "Furthermore, based on the ATTICA cross-sectional study involving 853 individuals, a positive correlation was observed between the Zung Self-Rating Depression Scale and CRP." (PMID 31019266, 2020). "While CRP is commonly used as inflammatory biomarker in axSpA, we cannot rule out CRP is not appropriate as a biomarker to identify a potential link between inflammation and depression in this disease." (PMID 32993799, 2020). "Most studies investigating inflammatory markers of depression have focused on CRP and IL-6." (PMID 33255237, 2020). "Recent evidence in patients with major depressive disorder demonstrates that peripheral CRP and inflammatory cytokines are strongly correlated with CSF markers, which suggests that peripheral markers may reflect similar findings in the central nervous system." (PMID 32153436, 2020). "Individuals in the increasing, compared with low, CRP group had a higher risk of ICD-10 diagnosis of depression at 18 years, but this was not statistically significant; adjusted OR 1.33 (95% CI, 0.73–2.39)." (PMID 31707310, 2020). "A subgroup analysis revealed that higher CRP levels may be characteristic of depressed men, atypical depression, depression with somatic symptoms, depressed patients with a history of childhood trauma and cumulative depressive episodes." (PMID 33255237, 2020). "C-reactive protein (CRP) and Interleukin 6 (IL-6) are common inflammatory markers, and elevated levels of CRP and IL-6 are associated with increased risk for psychological distress and depression." (PMID 32009956, 2019). "The combined effect of smoking and hs-CRP on depression differed between men and women." (PMID 30760746, 2019). "Depression itself can also trigger subsequent CRP elevation." (PMID 30760746, 2019).
depression (continued). "Although these data demonstrate that CRP is robustly associated with treatment-resistant depression, we do not claim that CRP is necessarily the best of all possible peripheral blood biomarkers of treatment-resistant depression." (PMID 29764522, 2019). "Moreover, serum IL-6 and CRP levels were observed to be positively correlated (r = 0.452; p = 0.043) with each other in depression." (PMID 30899619, 2019). "Moreover, observing elevated peripheral IL-6 and CRP levels would have promoted the psychoneuroimmunology theory as a contributing factor for the development of depression." (PMID 30899619, 2019). "This explanation can be applied to our findings of a lack of associations between CRP and telomere length in both men and women with depression." (PMID 31109116, 2019). "It will therefore be interesting to follow the outcome of an ongoing randomized controlled trial addressing the effects of a single administration of single-dose of a humanized monoclonal antibody against the IL-6 receptor in patients with depression and serum concentrations of CRP ≥ 3 mg/L." (PMID 30769887, 2019). "Ham-D: Hamilton Depression Rating Scale; IL-6: Interleukin-6; CRP: C-reactive protein; N: Number." (PMID 30899619, 2019). "A previous study revealed that more than one-third of schizophrenia, unipolar depression, bipolar depression, and bipolar mania had CRP level >3 mg/L, and suggested that it might be related to increased risk of cardiovascular events in those patients." (PMID 30760746, 2019). "Furthermore, inflammatory markers such as CRP, IL-6, and TNF-α have been associated with development or severity of psychiatric disorders such as depression, psychosis, and bipolar disorder." (PMID 31170007, 2019). "By design we have focused on dichotomous measure of inflammation, so we cannot comment on the distributions of continuous CRP values in patients/controls; these have been subject to previous meta-analyses reporting higher mean levels of CRP in depression compared with controls." (PMID 31258105, 2019). "We searched the PubMed database from its inception to July 2018, and selected studies that assessed depression using a validated tool/scale, and allowed the calculation of the proportion of patients with low-grade inflammation (CRP >3 mg/L) or elevated CRP (>1 mg/L)." (PMID 31258105, 2019). "We were motivated to test the hypothesis that the clinically defined subgroup of patients with treatment-resistant depression would have the most abnormally increased CRP." (PMID 29764522, 2019). "Based on logistic regression analysis, a positive association was found between poor dental health and depression that was independent of CRP and Body Mass Index (BMI)." (PMID 30998794, 2019). "Measurement of CRP levels could inform patient selection in RCTs of anti-inflammatory drugs for depression." (PMID 31258105, 2019). "Moreover, abnormal body weight, both under- and overweight, has been suggested to profoundly influence the relationship between CRP and depression." (PMID 30760746, 2019). "Recent evidence suggests that the relationship between depression and inflammation is symptom-specific, with the fatigue-type symptoms being most strongly associated with C-reactive protein, but this effect was absent in those using antidepressant medication." (PMID 29807551, 2019). "Also, TNF-α release as an inflammatory marker has been documented in patients with idiopathic major depression additional to circulating interleukin (IL)-1, IL-6, and C-reactive protein (CRP), which correlates with depression severity." (PMID 30866491, 2019). "Consistently, in our previous study, administration with nesfatin-1 could induce depression-like behaviors, accompanied with the increased plasma concentrations of IL-6 and CRP." (PMID 32009956, 2019).
depression (continued). "Many studies have reported an increase in proinflammatory cytokines such as interleukin (IL)-1, IL-6 and tumour necrosis factor-alpha and increases in the acute phase protein C-reactive protein (CRP) in patients with major depressive disorder (MDD) and among those exposed to maltreatment." (PMID 30762500, 2019). "In multivariate logistic regression analysis, the association between hs-CRP and depression was significant in men without or with one chronic medical disease (adjusted OR 2.12; 95% CI 1.06–4.24; P = 0.033)." (PMID 30760746, 2019). "A study conducted in Germany reported that depression is considerably associated with CRP in obese men but not in non-obese men14." (PMID 30760746, 2019). "There were studies measuring the effects of NTCT on depressive syndromes (n=12), cortisol (n=2), 5-HT (n=3), G-protein (n=1), cytokine (n=3), brain functional connectivity (n=2), brain activity (n=1), CRP (n=1), and HRV (n=1)." (PMID 31223326, 2019). "Indeed, proinflammatory cytokines, such as interferon-γ (IFN-γ), IL-2, TNF-α, and inflammatory markers such as C reactive protein (CRP), have been linked to higher risk of depression." (PMID 29941795, 2018). "While higher levels of the systemic inflammatory marker IL-6 in childhood are associated with an increased risk of developing depression and psychosis in young adulthood, the results were non-significant for CRP." (PMID 30190688, 2018). "If the variant were associated with IL-6, CRP, depression, and psychosis, but not with the confounders, this would indicate that the variant affects psychiatric risk by altering levels of inflammation." (PMID 29197507, 2018). "We show that Asp358Ala is strongly associated with serum concentrations of IL-6 and CRP, but not with any of the risk factors commonly linked with inflammation, depression or psychosis." (PMID 29197507, 2018). "Furthermore, Pearson’s test revealed a potential relationship between the depression-like behavior, the plasma CRP concentration, and the protein expressions of BDNF, Copine 6, synapsin I, or synaptotagmin I in the hippocampus or the PFC." (PMID 30429764, 2018). "We predicted that if IL-6 were related to depression/psychosis risk causally, rather than due to confounding, Asp358Ala would be associated with risk of these disorders, serum IL-6, CRP levels, but not with any of the confounders." (PMID 29197507, 2018). "The genetic variant is strongly associated with serum IL-6 and CRP levels, but not with any common confounders of the inflammation–depression relationship such as sex, social class, ethnicity and body mass index." (PMID 30244217, 2018). "Therefore, new chronic diseases are likely to affect patients with depression due to poor self-management as well as the presence of biological inflammatory mediators, such as IL-6 and C-reactive protein (CRP)." (PMID 29070021, 2017). "A previous study using blood-derived markers observed that poor cognitive performance was associated with elevated inflammatory cytokines, but not CRP, among patients with depression." (PMID 28694011, 2017). "Elevated CRP levels are associated with somatic (e.g. fatigue, anorexia, altered sleep) rather than psychological symptoms of depression in general population and in cancer patients who develop depressive symptoms after interferon treatment." (PMID 28418288, 2017). "The minor alleles of rs1130864 (TT) and rs1417938 (AA) were protective against depression in women, and were associated with lower levels of circulating CRP in men, but not women." (PMID 27555379, 2017). "Conversely, depression in men was associated with lower body fat and 49% higher CRP levels compared to men without depression." (PMID 29190710, 2017). "In our study, we found depression among 51 patients with high CRP levels." (PMID 28487875, 2017).
depression (continued). "A longitudinal study (in women) carried out by Pasco and colleagues reported a positive association between high baseline CRP levels and increased risk of de novo major depression, in those with no previous history of depression." (PMID 29190710, 2017). "In addition to treating depression, sertraline is capable to reduce pro-inflammatory cytokines and CRP." (PMID 28487875, 2017). "Patients with ESRD and depression, have higher levels of CRP and serum ferritin levels." (PMID 28487875, 2017). "Therefore, further analyses are needed to identify the BMI-specific relationship between serum CRP and depression." (PMID 28128231, 2017). "However, in a study on patients with coronary heart disease and comorbid major depression, the increase in CRP levels by sertraline therapy was found." (PMID 28487875, 2017). "The authors concluded that CRP is not a mediating factor between depression and inflammation, and cannot be used as a diagnostic biomarker for depression." (PMID 27555379, 2017). "One ‘type’ of depression generating substantial interest today focuses on patients with high levels of inflammatory burden, indicated by elevated levels of C-reactive proteins (CRP) and pro-inflammatory cytokines such as interleukin 6 (IL-6)." (PMID 27765060, 2016). "Likewise, van den Biggelaar and colleagues showed that baseline levels of CRP significantly predicted incident depression at 5-year follow-up in elderly participants of >85 years old." (PMID 25877654, 2016). "Self-esteem remained significantly associated with IL-6, CRP, and MMP-9 also after adjustment for hopelessness, vital exhaustion, or depression using dichotomy scale and with marginal significance for IL-6 (p = 0.06) and CRP (p = 0.061) after control for depression using continuous scale." (PMID 26979423, 2016). "While depression was significantly associated with CRP, current PTSD was not, which contradicts some previous findings." (PMID 27493807, 2016). "A significant association between C-reactive protein levels and major depression was noted after 14 studies and this did not change after addition of six more studies (d = 0.47, p < 0.0001)." (PMID 26065825, 2015). "Our study demonstrated that elevated serum CRP was one mechanism whereby anxiety / depression may lead to the development of storage LUTS." (PMID 26445118, 2015). "Similarly, the CRP–major depression relationship is robust and has been unaltered since 2012 after addition of six more recent publications." (PMID 26065825, 2015). "Adjusting for insulin sensitivity (HOMA-%S) and hs-C reactive protein attenuated these associations, but depression and CVD risk did not." (PMID 26167206, 2015). "Our cumulative meta-analysis of four inflammatory markers sought to bring together the findings from studies on the co-occurrence of elevated systemic levels of interleukins 6 and 1β, tumour necrosis factor α and C-reactive protein and major depressive disorders." (PMID 26065825, 2015). "Whether CRP levels at one month predict fatigue scores at six and 12 months was explored by multiple linear regression, with anxiety, depression, and daily step counts as covariates." (PMID 26599129, 2015). "IL-6, together with CRP, has received much attention in the pathogenesis of depression." (PMID 26617482, 2015). "Also, a positive correlation of C-reactive protein (CRP) with depression, unrelated to type 1 diabetes, in children and adolescents supports an interaction of emotional stress, systemic inflammation and neuroinflammation." (PMID 26831554, 2015). "In an analysis of the 2009-2010 NHANES dataset, patients with depression had higher levels of CRP." (PMID 26770976, 2015). "We acknowledge that this study has a limited number of patients that limit the power of some of statistical analyses and conclusions, namely in showing associations between clinical parameters and MDD occurrence (i.e. interaction between CRP and depression depending on the gender)." (PMID 25888123, 2015).